SOST (sclerostin)
Diseases named in the same sentence as SOST in open-access papers (continued):
Sharing a sentence is not in itself a finding about the gene and the disease.
breast carcinoma (continued). "Previous studies have shown elevated levels of circulating SOST in breast cancer patients, particularly in TNBC patients." (PMID 36581888, 2022). "Our data provide a proof of concept that SOST is a promising target for the treatment of primary breast cancer foci and bone metastases." (PMID 36581888, 2022). "Elevated sclerostin levels in metastatic breast cancer suppress bone formation through inhibition of the Wnt-signaling pathway, implicating its role in the pathogenesis of osteolytic lesions." (PMID 35160258, 2022). "At a molecular level, S6 appeared to occupy an important pocket of SOST to block its interaction with STAT3 in breast cancer cells." (PMID 36581888, 2022). "Breast cancer cells in bone metastasis regions reportedly expressed sclerostin, and treatment of breast cancer cells with anti-sclerostin antibodies inhibited the proliferation and migration of these cells in cultures." (PMID 35563281, 2022). "First, we characterized SOST protein expression in primary foci of 422 breast cancer specimens by immunohistochemistry (IHC)." (PMID 36581888, 2022). "Mechanistically, SOST promoted the proliferation and bone metastasis of breast cancer cells by activating downstream signaling pathways." (PMID 36581888, 2022). "Anti-sclerostin antibodies reduced bone metastasis of breast cancer cells with the suppression of bone destructions." (PMID 35563281, 2022). "Sclerostin is typically secreted by osteocytes, but breast cancer cells gain the ability to secrete the inhibitor when in the bone marrow niche by activating RUNX2/CBFβ signaling." (PMID 34685470, 2021). "A recent prospective study showed that postmenopausal women with hormone receptor positive early breast cancer treated with aromatase inhibitors had an increase in serum sclerostin levels after 24 months of treatment." (PMID 34290287, 2021). "In breast cancer cells, another antagonist of Wnt/β-catenin, sclerostin, inhibits osteoblast differentiation." (PMID 34685470, 2021). "A significant positive correlation between serum sclerostin and BMD of the lumbar spine was also observed in postmenopausal breast cancer patients treated with aromatase inhibitors, where sclerostin levels reportedly increased 46% due to treatment." (PMID 34290287, 2021). "Meanwhile, SOST expression is increased in breast cancer with bone metastasis, and the SOST antibody is reported to effectively suppress bone metastasis in breast cancer." (PMID 32674405, 2020). "Preclinical studies have shown a decreasing metastatic breast cancer burden in the mice bones with anti-sclerostin treatment." (PMID 33123472, 2020). "A monoclonal antibody to SOST, romosozumab, is being used for osteoporosis treatment in clinical practice, and further study is needed in order to implement its use in breast cancer patients with bone metastasis." (PMID 32674405, 2020). "The Wnt inhibitor sclerostin (SOST) is secreted by breast cancer cells and acts to inhibit the differentiation of osteoblasts thus promoting osteolysis." (PMID 32751181, 2020). "The results indicate the usefulness of sclerostin inhibition as a therapeutic option for breast cancer patients." (PMID 32640686, 2020). "This short non-coding microRNA promotes metastasis-related molecular properties in MDA-MB-231 aggressive breast cancer cells, by targeting sclerostin and secreted frizzled-related protein 2 (SFRP2), which greatly enhances Wnt signaling." (PMID 32640686, 2020). "There is increasing evidence suggesting a role of sclerostin in myeloma bone diseases and breast cancer bone metastasis-mediated complications." (PMID 32733380, 2020). "Micro-RNA-218 is secreted by breast cancer cells within extracellular vesicles and mechanistically acts to inhibit expression of the proteins sFRP-2 and Sclerostin which are key inhibitors of Wnt-family signalling." (PMID 32751181, 2020).
breast carcinoma (continued). "Inhibiting SOST expression using the unique design of zoledronic acid-loaded nanoparticles targeting osteocytes attenuates early breast cancer metastasis to bone." (PMID 32708317, 2020). "Breast cancer cells undergo a phenotypic change in the bone by assuming osteomimetic properties, including the ability to release sclerostin." (PMID 32640686, 2020). "Other interesting studies on sclerostin were focused on the role of miR-218 in metastatic bone disease from breast cancer." (PMID 32640686, 2020). "In this study, we observed a significantly increased level of sclerostin in the plasma of patients with breast cancer osseous metastasis compared with that of localized breast cancer and breast benign tumor." (PMID 28900298, 2017). "Our data suggest the role of sclerostin in breast cancer cell migration, invasion and metastasis to bone." (PMID 28900298, 2017). "We next quantified sclerostin in the plasma of breast cancer patients and matched health individuals by ELISA." (PMID 28900298, 2017). "Osteolytic cancer cells, such as breast cancer cells, overexpress Sclerostin (SOST) or Dickkopf1 (Dkk1), which play inhibiting roles in the Wnt signaling pathway, leading to downregulation of cell proliferation and differentiation." (PMID 28303941, 2017). "In this study, micro-CT was performed to explore the presence of micro-structure of femoral bone in mice, and to evaluate sclerostin induced bone osteolysis in breast cancer." (PMID 28900298, 2017). "In breast cancer patients, mainly in the cytoplasm of tumor cells, 12 (80%) of samples were weakly positive for sclerostin." (PMID 28900298, 2017). "Significantly upregulated expression of sclerostin was observed in BCBM compared with localized breast cancer and benign breast tumor, which was further confirmed by Western blot analysis." (PMID 28900298, 2017). "Breast cancer cells make sclerostin and DKK1, whereas serum DKK1 is increased in patients and contributes to osteolytic bone destruction in breast cancer bone metastases." (PMID 25757219, 2014). "We also show that Runx2/CBFβ regulates expression of the Wnt antagonist sclerostin and thus reveal a mechanism by which Runx2 mediates osteoblast inhibition by breast cancer cells." (PMID 22032690, 2011). "We also show that Runx2-dependent inhibition of osteoblast differentiation by breast cancer cells is mediated through the Wnt antagonist, sclerostin." (PMID 22032690, 2011). "Runx2 and CBFβ are required for the expression of genes that mediate the ability of metastatic breast cancer cells to directly modulate both osteoclast (GM-CSF, IL-11) and osteoblast (sclerostin) function." (PMID 22032690, 2011). "The authors concluded that sclerostin inhibition may reduce the potential of breast cancer tumor cells to form bone metastases." (PMID 38247829, 2024). "The effect of sclerostin on the proliferation, migration, and invasion abilities of two different breast cancer cell lines (MCF-7 and MDA-MB-231) was investigated by inhibiting sclerostin with an inhibitory antibody at different doses (1 and 4 μg/mL) and time periods (1, 2 and 3 days)." (PMID 38247829, 2024). "Nonetheless, this hypothesis contrasts with the observation that breast cancer metastases exhibited the same growth rate in control and SOST KO mice." (PMID 37174109, 2023). "Similarly, in breast cancer cells, genetic overexpression of sclerostin or DKK-1 leads to more bone metastases and bone disease." (PMID 37174109, 2023). "Another study revealed that sclerostin inhibition alleviates breast cancer–induced bone metastases and muscle weakness, which indicated that sclerostin not only inhibited bone formation, but also might have a negative effect on muscle." (PMID 36456918, 2022). "Considering the effect of SOST on breast cancer cell proliferation and the presence of SOST in the cytoplasm, we speculate that SOST may activate the RAS and TGF-β signaling pathways by interacting with intracytoplasmic transcription factors, such as STAT3." (PMID 36581888, 2022).
breast carcinoma (continued). "Together, these results suggest that SOST in breast cancer cells may promote the proliferation of SCP2 cells by activating the TGF-β/RAS signaling, and promotes bone metastasis by upregulating CXCR4 expression." (PMID 36581888, 2022). "Furthermore, SOST acts as oncogenic factor to induce breast cancer bone metastasis as well as osteolysis and inhibition of SOST alleviates the breast cancer-induced bone metastasis and muscle weakness." (PMID 36581888, 2022). "This novel finding supports the notion that SOST acts as oncogenic factor to promote breast cancer bone metastasis and suggests that SOST may be a therapeutic target for inhibiting breast cancer bone metastasis." (PMID 36581888, 2022). "Treatment of bone marrow derived mesenchymal stem cells and MC3T3 cells with conditioned media from MDA-231 breast cancer cells suppressed osteoblast differentiation, while conditioned media pretreated with anti-sclerostin antibody attenuated the suppression of differentiation." (PMID 34503118, 2021). "Interestingly, sclerostin was shown to be a transcriptional target of Runx2 and secreted by both breast cancer and myeloma cells." (PMID 34503118, 2021). "MiR-218 might act on sclerostin produced by breast cancer cells to reduce osteoblast function and differentiation." (PMID 32640686, 2020). "In conclusion, we have identified increased secretion of sclerostin by breast cancer cells." (PMID 28900298, 2017). "Here, we found that sclerostin was overexpressed in breast cancer tumor tissues and cell lines." (PMID 28900298, 2017). "Taken together, sclerostin promotes breast cancer cell migration, invasion and bone osteolysis." (PMID 28900298, 2017). "Inhibition of sclerostin by Scl-Ab suppresses migration and invasion of breast cancer cells." (PMID 28900298, 2017). "Inhibition of sclerostin may serve as an efficient strategy for interventions against breast cancer bone metastasis or osteolytic bone diseases." (PMID 28900298, 2017). "Production of sclerostin by breast cancer cells blocks osteoblast differentiation." (PMID 25757219, 2014). "Our finding that metastatic breast cancer cells express sclerostin, therefore, suggests that therapies to target sclerostin might also improve healing of osteolytic lesions in breast cancer patients." (PMID 22032690, 2011). "However, it is unclear whether SOST can be used as a therapeutic target for bone metastases of breast cancer, and whether small molecule compounds that target SOST in breast cancer cells can inhibit breast cancer bone metastasis." (PMID 36581888, 2022). "Thus, SOST silencing inhibited the adhesion onto the bone matrix and bone metastasis in mice, suggesting that SOST may be a critical factor for breast cancer bone metastasis." (PMID 36581888, 2022). "Zhu and colleagues reported that sclerostin was over-expressed in breast cancer tumor tissues and cell lines and that the inhibition of sclerostin by specific antibody significantly reduced migration and invasion of breast cancer cell lines in a time-and dose-dependent manner." (PMID 32640686, 2020). "Hence, SOST may be a specific marker for breast cancer bone metastasis." (PMID 36581888, 2022). "To identify potential therapeutics, we screened inhibitors of the interaction of SOST with STAT3 from a small chemical molecule library and tested the inhibitory effects of one inhibitor on breast cancer growth and bone metastasis in vitro and in vivo." (PMID 36581888, 2022). "Using computational screening, we identified a candidate therapeutic compound that disrupted the interaction of SOST with STAT3 to inhibit STAT3 phosphorylation and reduce breast cancer bone metastasis." (PMID 36581888, 2022). "We selected breast cancer SCP2 cells that are prone to bone metastasis to explore the molecular mechanisms and found that SOST promoted the proliferation of breast cancer cells by enhancing the STAT3/TGF-β/KRAS signaling." (PMID 36581888, 2022).
breast carcinoma (continued). "Promising preclinical data have demonstrated a reduced metastatic breast cancer burden in the bones of female immune-compromised SCID mice, in addition to a prolonged survival upon treatment with anti-sclerostin antibody." (PMID 32092997, 2020). "The particles attenuate tumorigenesis and osteoclast formation in a breast cancer bone metastasis model by inhibiting RANKL and sclerostin expression in osteocytes." (PMID 32708317, 2020). "It is likewise reported that prostate and breast cancer cells produce DKK-138, 39 which, like sclerostin, inhibits Lrp5 (activator of the Wnt/ß-catenin pathway)." (PMID 27666393, 2016). "It is, therefore, likely that both sclerostin and DKK1 cooperate to inhibit Wnt signaling in osteolytic lesions in breast cancer bone metastases." (PMID 22032690, 2011). "Breast cancer cells frequently release Wnt inhibitors like DKK-1 and SOST." (PMID 40426987, 2025). "Sclerostin was increased in the breast cancer metastatic cell line, MDA-MB 231, and in the nonmetastatic cell line, MCF-7, due to the abnormal overexpression of Runx2, which binds to the proximal promoter of the SOST gene." (PMID 35160258, 2022). "However, osteocytes secrete various growth factors and cytokines known to have key roles in breast cancer cell migration, proliferation, and the vicious cycle (e.g., RANKL, MMPs, TNFα, sclerostin)." (PMID 32092997, 2020). "Previous studies have shown that Runx factors directly regulate SOST and CSF-2 expression in other cell-types but they are not known targets of Runx2 in breast cancer cells." (PMID 22032690, 2011). "While the role of GM-CSF as an activator of osteoclasts in breast cancer bone metastasis is well established, the role of sclerostin has not been investigated." (PMID 22032690, 2011). "Moreover, anti-sclerostin treatment in mice with intrafemoral breast cancer tumors did not affect tumor growth rate but improved overall survival." (PMID 37174109, 2023). "Because the TGF-β/SMAD3 signaling can upregulate CXCR4 expression in breast cancer, promoting metastasis, and its ligand CXCL12 is enriched in the bone marrow microenvironment, we evaluated whether SOST silencing could change in the expression of these factors in SCP2 cells." (PMID 36581888, 2022). "However, treatment with anti-sclerostin antibodies failed to suppress tumor growth in xenograft model mice, in which breast cancer cells were injected into their bone marrows." (PMID 35563281, 2022). "We first demonstrated that expression of SOST and CSF-2 could be induced in non-metastatic MCF-7 breast cancer cells by heterologous expression of Runx2." (PMID 22032690, 2011).
Obesity (34 papers, 2014 to 2026). Accumulation of substantial excess body fat. "Obesity is a well-known cardiovascular risk factor, but a relationship between increased sclerostin levels and vascular risk has also been recently reported." (PMID 35807755, 2022). "It is also the first study that demonstrates the association of FGF-23, osteopontin, NGAL and sclerostin concentrations with obesity, cardiovascular risk factors, glucose homeostasis and BMR following a 1-year life-style intervention program." (PMID 36145151, 2022). "This cross-sectional analysis suggests that obesity protects the lumbar spine from bone loss caused by menopause possibly through pathways involving sclerostin." (PMID 34679612, 2021). "Sclerostin was positively associated with anthropometric indexes of obesity, and inversely with IR, namely homeostatic model assessment for peripheral insulin sensitivity (HOMA2%S) (r = −0.218; p = 0.045)." (PMID 33671861, 2021). "We aimed to evaluate the associations between serum sclerostin and anthropometric and metabolic parameters in children and adolescents with obesity." (PMID 34572220, 2021). "Firstly, we have observed a significant association between serum sclerostin levels and anthropometric indexes of obesity." (PMID 33671861, 2021). "Consistently, either sclerostin deficiency or the administration of sclerostin antibody protected mice from HFD-induced obesity, hyperglycemia, hyperlipidemia, insulin resistance, and fat deposition in the liver." (PMID 32544571, 2020). "This study aims to examine the circulating levels of SOST in a multiethnic population living in Kuwait and to elucidate the relationship between SOST levels, obesity, T2DM, and ethnic background." (PMID 38711986, 2024). "BMSCs treated with AGEs, fat mass and obesity associated (FTO) protein knockdown and sclerostin (SOST) interference were evaluated by quantitative polymerase chain reaction, western blot, immunofluorescence, alkaline phosphatase and Alizarin red S staining." (PMID 37925419, 2023). "The purpose of this study was to examine subcutaneous WAT (scWAT) sclerostin content and Wnt signaling in response to exercise training in young men with obesity." (PMID 35312183, 2022). "Together, these results provide novel context to sclerostin’s endocrine role, which appears to be responsive to acute exercise (iWAT) and diet induced obesity/insulin resistance (eWAT) depending on the depot." (PMID 36685192, 2022). "Although this relationship seems to conflict with the intrinsic osteopenic effects of sclerostin, this finding suggests a potential role of this hormone in the protective effects elicited by obesity on lumbar spine at menopause." (PMID 35873004, 2022). "As stated, in agreement with the invitro and experimentally documented information, we did find a significant relationship between fat amount or obesity and sclerostin levels." (PMID 35807755, 2022). "The main results of this study show that serum sclerostin increases in relation to liver function impairment and that there is an independent direct relationship of sclerostin levels with obesity and fat mass, especially gynoid and android fat mass." (PMID 35807755, 2022). "The relation of sclerostin with fat and obesity is in accordance with the current knowledge about the effects of sclerostin on intermediate metabolism." (PMID 35807755, 2022). "In contrast, sclerostin increased significantly with weight and showed the highest values in the patients suffering from obesity when compared to the underweight and normal-weight subjects (p < 0.001)." (PMID 35267956, 2022). "In this study, we examined sclerostin content in serum and subcutaneous adipose tissue both pre‐ and post‐exercise training in humans with obesity." (PMID 35312183, 2022). "On the other hand, the high sclerostin levels with low SIRT1 in our cohort of patients with obesity fit with the significant downregulation of osteoblasts’ SIRT1 following mechanical stress." (PMID 35267956, 2022).